ERCC4 (ERCC excision repair 4, endonuclease catalytic subunit)
Diseases named in the same sentence as ERCC4 in open-access papers (continued):
Sharing a sentence is not in itself a finding about the gene and the disease.
gastric cancer (11 papers, 2012 to 2025). A primary or metastatic malignant neoplasm involving the stomach. "The current evidence showed that four SNPs of the ERCC4 gene (rs744154, rs1800067, rs2276466, and rs1799801) were significantly associated with risk of three cancers (bladder cancer, glioma, and gastric cancer)." (PMID 36033436, 2022). "For the association between ERCC4 polymorphisms and cancer risk, previous studies have mainly focused on a functional SNP rs1800067G>A, and few case-control studies reported on gastric cancer to date." (PMID 23166636, 2012). "Additionally, increased ERCC4 expression is associated with CDDP resistance in gastric cancer cells, aligning with our findings." (PMID 40076972, 2025). "We executed meta-analysis on the correlation between 12 variants of ERCC4 and the risk of 13 types of cancer, and four SNPs (rs744154, rs1800067, rs2276466, and rs1799801) were figured out to be significantly associated with risk of three cancers (bladder cancer, gastric cancer, and glioma)." (PMID 36033436, 2022). "Briefly, our research offers comprehensive epidemiological evidence that common variants of the ERCC4 and ERCC5 genes show association with the predisposition of bladder cancer, esophageal cancer, laryngeal cancer, uterine cancer, and gastric cancer." (PMID 36033436, 2022). "Consistently, vital studies have indicated that miR-192-5p plays a role in the resistance of EC and gastric cancer to chemotherapy, which reverses cisplatin resistance by targeting ERCC3 and ERCC4 in gastric cancer lines." (PMID 33708127, 2021). "Many researches have mentioned the role of ERCC4 in cancers, such as bladder cancer, gastric cancer and oral cancer." (PMID 34993023, 2021). "Forced expression of miR-192-5p in SGC7901/DDP cells can significantly inhibit the expression of ERCC4, making the gastric cancer cells more sensitive to cisplatin in vitro and in vivo." (PMID 34993023, 2021). "More interestingly, several association studies also found that SNPs located in DNA repair related genes including ERCC4, ERCC6, Ku70m, APE1, XRCC1, and XPD exhibited a differential effect between genders on gastric cancer susceptibility." (PMID 26402912, 2015). "Logistic regression analysis of associations between selected ERCC1 and XPF/ERCC4 SNPs and gastric cancer risk in an Eastern Chinese population." (PMID 23166636, 2012). "In summary, this large hospital-based case-control study provided statistical evidence that ERCC1 rs2298881 and rs11615 SNPs, but not ERCC4 SNPs, were associated with gastric cancer risk in an Eastern Chinese population, particularly for never-drinkers, patients with NGCA and early clinical stages." (PMID 23166636, 2012). "Upregulation of miR187 in gastric cancer significantly downregulated the protein expression of Smad4, TGF-β1, and NER components (ERCC3 and ERCC4), which boosted the cisplatin sensitivity." (PMID 40303493, 2025). "MiR-138-5p regulated the cisplatin resistance by modulating the expression of the DNA repair proteins ERCC4 and ERCC1 in gastric cancer cells." (PMID 34993023, 2021).
ovarian carcinoma (10 papers, 2013 to 2024). A malignant neoplasm originating from the surface ovarian epithelium. "For example, increased expression of the NER genes ERCC1 and ERCC4/XPF is associated with cisplatin resistance in ovarian cancer cells, while knockdown of ERCC1 enhanced cellular sensitivity to cisplatin." (PMID 34645978, 2021). "In the present study, we performed a hypothesis-based association to explore the impact of SNPs in these core genes (XPA, XPC, XPG, ERCC1, ERCC2, and ERCC4) on the risk of ovarian cancer by genotyping a pool of 17 SNPs in 89 patients and 356 controls." (PMID 29669843, 2018). "We identified significant high-frequency mutations in the ERCC4, CHEK2, and PDGFRA genes in young patients with ovarian cancer." (PMID 38817903, 2024). "In this study, we aim to gain insight in the germline mutation spectrum of ATM, BARD1, BRIP1, ERCC4, PALB2, RAD51C and RAD51D in breast and ovarian cancer families from Spain." (PMID 32756499, 2020). "In ovarian cancer, ERCC4 mRNA expression has previously been shown to be tightly correlated with ERCC1 mRNA expression, indicating that the mechanisms regulating the expression of these genes are linked." (PMID 24144331, 2013). "Therefore, we conducted genotyping for 17 SNPs of six NER core genes (XPA, XPC, XPG, ERCC1, ERCC2, and ERCC4) in 89 ovarian cancer cases and 356 cancer-free controls." (PMID 29669843, 2018).
XFE progeroid syndrome (9 papers, 2010 to 2024). A syndrome characterized by aged bird-like facies, lack of subcutaneous fat, dwarfism, cachexia and microcephaly. "XFE progeroid syndrome results from mutations in ERCC4/FANCQ, causing reduced expression of XPF-ERCC1, a heterodimeric DNA repair endonuclease required for NER and the repair of some DNA DSBs." (PMID 37762580, 2023). "Defects of ERCC4 are the cause of xeroderma pigmentosum complementation group F (XP-F) [MIM:278760], and the XFE progeroid syndrome (XFEPS) [MIM:610965] which includes stunted growth and microcephaly." (PMID 24465539, 2014).
bladder cancer (8 papers, 2008 to 2025). "Western blot analysis revealed that exogenous CXCL14 significantly increased ERCC4 expression in bladder cancer cells in CXCL14-deficient CAFs." (PMID 40898244, 2025). "In our study, we observed transcriptional upregulation of ERCC4 in CXCL14-induced chemoresistant bladder cancer cells." (PMID 40898244, 2025). "Specifically, CXCL14 activates the CCR7/JAK2/STAT3 axis, leading to the upregulation of ERCC4 transcription, which promotes DNA damage repair in bladder cancer cells, thereby facilitating the development of chemoresistance." (PMID 40898244, 2025). "The overexpression of ERCC4 led to decreased sensitivity to cisplatin and reduced DNA damage in bladder cancer cells." (PMID 40898244, 2025). "Mechanistically, hnRNPK regulated various functions in bladder cancer by directly mediating cyclin D1, G0/G1 switch 2 (G0S2), XIAP‐associated factor 1, and ERCC excision repair 4, endonuclease catalytic subunit (ERCC4) transcription." (PMID 27862976, 2017). "Garcia-Closas evaluated the influence of common genetic variation in the NER pathway on bladder cancer risk by analyzing 22 single nucleotide polymorphisms (SNP) in seven NER genes (XPC, RAD23B, ERCC1, ERCC2, ERCC4, ERCC5, and ERCC6)." (PMID 19055767, 2008). "Additionally, ERCC4 knockdown in T24 cells alone increased the tumor sensitivity to cisplatin and reduced tumor burden in the bladder cancer model." (PMID 40898244, 2025). "Given that signaling pathways play important roles in the transcriptional modulation of key cellular regulators, we identified STAT3 as a potential transcriptional regulator of ERCC4, whichwas positively correlated with ERCC4 expression in bladder cancer patients in the TCGA cohort." (PMID 40898244, 2025). "Additionally, by comparing ERCC4 expression in different bladder cancer cell lines after continuous treatment and subsequent rhCXCL14 removal, we observed that rhCXCL14 consistently promoted ERCC4 overexpression, but this effect was maintained for only 24 h after rhCXCL14 was removed." (PMID 40898244, 2025). "Additionally, for the first time, we found that exogenous CXCL14 from CAFs could enhance the NER response of bladder cancer cells by upregulating ERCC4 expression." (PMID 40898244, 2025). "Collectively, our results suggest that CAF-derived CXCL14 targets CCR7 in bladder cancer cells, enhancing ERCC4 transcription through JAK2/STAT3 activation and subsequently binding to the ERCC4 promoter region." (PMID 40898244, 2025). "Mechanistically, CAF-secreted CXCL14 engaged CCR7 on bladder cancer cells, triggering STAT3 phosphorylation and consequently upregulating the DNA repair gene ERCC4 to promote cisplatin resistance." (PMID 40898244, 2025). "To explore the roles of ERCC4 and MRP2 in the development of drug resistance in bladder cancer cells, we modulated their expression in T24 and UM-UC-3 cells and confirmed the effects of their knockdown at the translational level." (PMID 40898244, 2025). "Western blot analysis revealed that deficient expression of CXCL14 in CAFs failed to increase the expression of ERCC4 and inhibited DNA damage-induced apoptosis in bladder cancer cells." (PMID 40898244, 2025). "Collectively, these findings indicate that hnRNPK enhances bladder cancer cell anti‐apoptosis and chemoresistance to cisplatin by regulating XAF1 and ERCC4 and that it may be a potential target for drug development." (PMID 27862976, 2017). "To investigate whether STAT3 binds to the promoter region of ERCC4 and how CXCL14 enhances its expression in bladder cancer cells, we overexpressed STAT3 in 293 T cells as an external validation and modulated STAT3 phosphorylation in T24 cells with rhCXCL14 or rhCXCL14 combined with STAT3i." (PMID 40898244, 2025).
lung carcinoma (8 papers, 2012 to 2024). "In the present study, we found that two rSNPs (ERCC1 rs3212924 and XPC rs2229090) were associated with PFS and one rSNP (ERCC4 rs1799798) associated with OS of NSCLC patients, and these associations were not previously reported for lung cancer." (PMID 28878296, 2017).
progeroid syndrome (7 papers, 2010 to 2025). A group of rare genetic disorders which mimic physiological aging, making affected individuals appear to be older than they are. "And ERCC4 illustrates a critical role in DNA interstrand crosslink repair, and pathogenic variants in this gene cause segmental progeroid syndromes." (PMID 32457595, 2020). "Mutation in XPF/ERCC4 can produce a progeria-like phenotype (XFE) characterized by the failure of the mutant XPF protein to properly translocate to the nucleus and to be recruited to sites of active DNA repair." (PMID 30658521, 2019).
pancreatic cancer (5 papers, 2013 to 2022). "A decreased pancreatic cancer risk was observed for carriers of ERCC4 R415Q and LIG3 G-39A minor alleles, while an increased risk was observed for the ATM D1853N allele." (PMID 24651674, 2014). "In addition, mechanistic studies of individual SNPs in CYP2A6, TNFA and ERCC4 genes would be useful to assess their contribution to the development of pancreatic cancer." (PMID 24651674, 2014). "We report an association of pancreatic cancer with DNA damage and associations with specific polymorphisms in genes involved in metabolism (CYP2A6), inflammation (TNFA), and DNA damage and repair (ERCC4)." (PMID 24651674, 2014).
colon cancer (4 papers, 2018 to 2021). "In colon cancer, high expression of ERCC4 was associated with significantly favourable OS than those with low ERCC4 expression in males." (PMID 29568775, 2018). "Colon cancer patients with high expression of ERCC4 showed significantly favourable OS than those with low ERCC4 expression according to multivariate analysis in males (adjusted HR = 0.54, 95% CI = 0.30–0.96, P = 0.035)." (PMID 29568775, 2018). "Colon cancer patients with high ERCC4 expression showed favorable OS in males (HR = 0.54, P = 0.035)." (PMID 29568775, 2018). "Colon cancer male patients with high ERCC4 expression showed favourable survival." (PMID 29568775, 2018).
endometrial cancer (4 papers, 2019 to 2025). Primary or metastatic malignant neoplasm involving the endometrium (mucous membrane that lines the endometrial cavity). "Other authors have associated ERCC4 mutations with endometrial cancer and colorectal; however, until now, the relatives with endometrial cancer have refused genetic testing." (PMID 32756499, 2020). "In our study, 8 patients were identified with pathogenic or likely pathogenic germline mutations in non-Lynch syndrome genes (MUTYH, GALNT 12, POLE, MPL, ATM, and ERCC4), which indicated that there may be other genes outside of Lynch syndrome associated with endometrial cancer." (PMID 30886832, 2019). "In addition, we identified 2 patients who had a deleterious germline mutation in Lynch syndrome genes (MLH1 and MLH2), and another 8 patients harbored germline mutations of 6 non-Lynch syndrome genes (MUTYH, GALNT12, POLE, MPL, ATM, and ERCC4) which may be associated with endometrial cancer." (PMID 30886832, 2019).
melanoma (4 papers, 2017 to 2023). A malignant, usually aggressive tumor composed of atypical, neoplastic melanocytes. "We found that several HRR-associated genes, including DDB2, RAD51, BRCA1, XRCC2 and BRCA2, are overexpressed in melanoma cells compared to primary melanocyte cultures, while the expression of the NER-associated genes XPA, ERCC1 and ERCC4 showed no clear differences." (PMID 32719412, 2020).
skin cancer (4 papers, 2017 to 2024). "In contrast, patients with XPF (ERCC4) have milder symptoms, with later onset of skin cancer, possibly due to the fact that XPF mutations are usually point mutations occasionally resulting in frameshift, leading to the unstable truncation of the XPF protein." (PMID 38516408, 2024).
head and neck squamous cell carcinoma (3 papers, 2012 to 2022). A squamous cell carcinoma that arises from any of the following anatomic sites: lip and oral cavity, nasal cavity, paranasal sinuses, pharynx, larynx, and salivary glands. "In this case-control study, we evaluated associations of four selected potentially functional SNPs in ERCC4 with risk of squamous cell carcinoma of the head and neck (SCCHN) in 1,040 non-Hispanic white patients with SCCHN and 1,046 cancer-free matched controls." (PMID 22848636, 2012).
cerebellar ataxia (2 papers, 2021 to 2023). A neurological syndrome characterized by clumsy and uncoordinated movement of the limbs, trunk, and cranial muscles. "So far, a few cases of ERCC4 gene variants, which are associated with nucleotide excision repair pathways, have been described in connection with symptoms of cerebellar ataxia." (PMID 36816046, 2023).
cervical cancer (2 papers, 2019 to 2022). A primary or metastatic malignant neoplasm involving the cervix. "A recent study analyzed the expression of XRCC1, ERCC2, ERCC4 and ERCC1 in cervical tissue samples and showed that the levels of both mRNA and protein were lower in squamous intraepithelial lesions and cervical cancer samples than in samples from control patients." (PMID 30674977, 2019).
Chorea (2 papers, 2023 to 2024). Chorea (Greek for 'dance') refers to widespread arrhythmic involuntary movements of a forcible, jerky and restless fashion. "However, the clinical phenotype with chorea and history of sun sensitivity suggests that the ERCC4 mutation is causally linked to the clinical phenotype." (PMID 39652212, 2024). "ERCC4 mutations are a particularly rare cause of late onset chorea." (PMID 39652212, 2024).
glioblastoma (2 papers, 2022 to 2025). The most malignant astrocytic tumor (WHO grade IV). "Germline MSH3 and ERCC4 mutation may induce a secondary osteosarcoma in glioblastoma patients." (PMID 36271359, 2022).
laryngeal carcinoma (2 papers, 2018 to 2022). Carcinoma that arises from the laryngeal epithelium. "Polymorphisms in other NER genes including ERCC1, ERCC2, ERCC3, ERCC4, ERCC5, and XPA have also been reported to pose as an increased risk in Laryngeal Cancer." (PMID 30410671, 2018).
lymph node metastasis (2 papers, 2020 to 2021). "A clonal driver mutation in MYCN (MIM: 164840; CRC-190), and subclonal driver mutations in ELF4 (MIM: 300775; 083-03), PTPRB (MIM: 176882; CRC-233 lymph node metastasis), FUS (MIM: 137070), and ERCC4 (MIM: 133520) in CRC-449 were all specific to metastatic tumours." (PMID 33053768, 2020).
meningioma (2 papers, 2014 to 2025). A generally slow growing tumor attached to the dura mater. "We revealed specific signatures in lower-grade meningioma such as NF2, AKT1E17K, and KLF4K409Q, and identified co-occurring mutations such as ATM-BIVM-ERCC5, PIK3C2B-SDHD, and ERCC4-MET." (PMID 40562609, 2025).
osteosarcoma (2 papers, 2022). A usually aggressive malignant bone-forming mesenchymal neoplasm, predominantly affecting adolescents and young adults. "It is also seen that the concentration of ERCC4 mRNA in peripheral blood cells is correlated with the response of osteosarcoma to chemotherapy." (PMID 36157228, 2022). "Earlier studies have shown that the ERCC4 gene is differentially expressed in osteosarcoma and normal tissues." (PMID 36157228, 2022). "Bioinformatic analysis showed the two germline mutations (MSH3 and ERCC4) induced deficiency in the DNA repair machinery, which resulting in the accumulation of mutations and may generate neoantigens contributing to the development of a secondary osteosarcoma in this case." (PMID 36271359, 2022). "In order to reveal the potential genetic mechanism of secondary osteosarcoma occurrence, we analysis the result of whole-exome sequencing and found 8 germline gene variations, which consist of 7 germline genes (including EPAS1, SETD2, MSH3, BMPR1A, ERCC4, CDH1 and AR)." (PMID 36271359, 2022).
sarcoma (2 papers, 2017 to 2018). A usually aggressive malignant neoplasm of the soft tissue or bone. "Interestingly, a truncating mutation in ERCC4 (p.Cys723*) was found in two patients with sarcoma diagnosed under age 25 years." (PMID 28878254, 2017). "We additionally identified at 16p13.1 a cryptic deletion (165 Kilobases) which included a single gene ERCC4 coding for Excision Repair 4, Endonuclease Catalytic subunit which is involved in germ line mutations and was recently associated with genetic predisposition in sporadic sarcoma." (PMID 29494553, 2018).
autosomal recessive cerebellar ataxia (1 paper, 2021). "Japanese patients homozygous for ERCC4 p.Arg799Trp or compound heterozygous with another variant were diagnosed with autosomal recessive cerebellar ataxias." (PMID 34503238, 2021).
cancers of oral cavity (1 paper, 2012). "For example, in the analyses by tumor sites, the ERCC4 rs2276466 and rs3136038 were only found to be associated with risk of oropharyngeal cancer but not for cancers of oral cavity, hypopharynx and larynx." (PMID 22848636, 2012).
deafness (1 paper, 2024). An inherited or acquired condition characterized by the complete loss of the ability to hear from one or both ears. "While the homozygous deletion in OTOA is a well-established cause of deafness, the pathogenicity of the ERCC4 variant identified in our patients is currently supported only by allele frequency data, in silico predictions, and clinical concordance." (PMID 39769235, 2024).
diabetes (1 paper, 2020). "Additionally, associations with CKD related pathologies, such as hypertension (GPX4, CYP11B2, ERCC4), cardiovascular disease, diabetes and cancer predisposition (ERCC2) were also observed." (PMID 31924810, 2020).
hearing loss (1 paper, 2024). "In addition to symptomatic treatment, regular surveillance especially for skin malignancies and hearing loss are key components in the care of patients with ERCC4 -related neurodegeneration." (PMID 39652212, 2024).
hereditary cancer (1 paper, 2020). Malignant neoplasms occurring in families at a rate greater than that expected by chance and caused by germline mutations in a specific gene. "A prospective cohort of 1021 unrelated cancer cases with clinical suspicion of hereditary cancer was screened for mutations in the following 14 FA genes: FANCA, FANCB, FANCC, FANCD2, FANCE, FANCF, FANCG/XRCC9, FANCI, FANCL/PHF9, FANCM, FANCP/SLX4, FANCQ/ERCC4, FANCR/RAD51 and FANCU/XRCC2." (PMID 32235514, 2020).
Hypertension (1 paper, 2020). The presence of chronic increased pressure in the systemic arterial system. "GPX4, CYP11B2, and ERCC4 genes were associated with hypertension." (PMID 31924810, 2020). "In addition, other genes were found to be associated with CKD related pathologies, such as hypertension (GPX4, CYP11B2, ERCC4), cancer predisposition (ERCC2), and cardiovascular disease (ERCC2)." (PMID 31924810, 2020).